CRIPTOP4 (CRIPTO pseudogene 4)
Synonyms: CR-4; CRIPTO-4; formerly TDGF4; TDGF1P4
Gene: Processed pseudogene on chromosome 6 (3,941,282 to 3,941,801, forward strand). Ensembl gene ENSG00000217566.
Diseases named in the same sentence as CRIPTOP4 in open-access papers:
CRIPTOP4 is named in the same sentence as 37 diseases in open-access papers, as found by Europe PMC text mining. Sharing a sentence is not in itself a finding about the gene and the disease.
CRIPTOP4 shares sentences with these, for which no sentence is quoted: infection (11 papers); tumor (5); HIV-1 infection (4); aplastic anemia (2); preeclampsia (2); Alzheimer disease (1); atherosclerosis (1); autoimmune conditions (1); bacterial infections (1); blood disorders (1); Burkitt lymphoma (1); cancer (1); chronic lymphocytic leukemia (1); co-infection (1); congenital neutropenia (1); COVID-19 (1); dengue (1); dyskeratosis congenita (1); experimental autoimmune encephalomyelitis (1); gastric cancer (1); hairy cell leukaemia (1); Hodgkins lymphoma (1); ischemic stroke (1); leukaemia (1); lupus (1); lymph node metastasis (1); lymphoma (1); melanoma (1); nasal polyps (1); neurodegenerative disease (1).
A further 7 diseases each share a sentence with CRIPTOP4 in 1 paper.